EGFR (epidermal growth factor receptor)
Diseases named in the same sentence as EGFR in open-access papers (continued):
Sharing a sentence is not in itself a finding about the gene and the disease.
cancer (continued). "Recently, accumulating evidence has shown that acquired resistance to chemotherapeutic drugs such as platinum, epidermal growth factor receptor tyramine kinase (EGFR-TK) inhibitors, and anaplastic lymphoma kinase (ALK) inhibitors is associated with increased PD-L1 expression in cancer cells." (PMID 32024543, 2020). "EGFR is a membrane protein, and numerous studies have revealed that it can translocate to the cytoplasm and mitochondria, and can be shuttled to the nucleus in cancers." (PMID 31936895, 2020). "The lack of significant toxicity of the MLD therapy in mice may be explained by the fundamentally different nature of MAPK pathway signalling between normal and EGFR mutant cancer cells." (PMID 32572029, 2020). "The combination of dasatinib with EGFR inhibitors is under investigation in other cancer types, as the ongoing Phase I clinical trial NCT00996723 evaluating the combination of the vandetanib and dasatinib during and after radiation therapy in diagnosed diffuse intrinsic pontine glioma." (PMID 32517369, 2020). "Former studies have revealed the regulatory function of LPAR3 and EGFR in cancers." (PMID 32231464, 2020). "Targeting EGFR in combination with conventional chemotherapy might be a promising strategy for the treatment of HNSCC through elimination of cancer stem cells." (PMID 31823521, 2020). "In cancer, the ERK/MAPK signal is abnormally activated by the upstream activation by epidermal growth factor receptor (epidermal growth factor receptor) and Ras GTPases (small guanosine triphosphatase), and it is involved in promoting cancer cell proliferation, survival, and metastasis." (PMID 32281236, 2020). "In conclusion, this study indicated that XLEP could suppress the proliferation of EGFR-TKI-resistant cancer cells and increase the ratio of M1/M2 macrophages by inhibiting autophagy to treat the drug-resistant EGFR-positive NSCLC." (PMID 32256661, 2020). "Therefore, to inhibit EGFR phosphorylation in cancer cells, many clinical applications have been stimulated to develop EGFR tyrosine kinase inhibitors (TKIs) such as erlotinib, gefitinib, and lapatinib." (PMID 32204508, 2020). "EGFR-expressing malignant tumors that are refractory under conventional chemotherapy and radiotherapy may benefit from targeted therapy with cetuximab." (PMID 32560337, 2020). "In addition to ITPR2, EGFR is frequently mutated or overexpressed in various cancer types, and in PDAC particularly, EGFR is essential for KRAS-driven pancreatic carcinogenesis." (PMID 32629766, 2020). "It is relevant to note that estrogen can cause trans-activation of EGFR via a non-genomic pathway acting through the membrane ER mERα to drive cell proliferation in many cancer types." (PMID 33363037, 2020). "Currently, EGFR is a promising candidate for therapeutic approaches against cancer." (PMID 32823532, 2020). "Such situations can be seen with the promising results of the combined utility of bevacizumab and erlotinib (epidermal growth factor receptor (EGFR)-TKI) for EGFR-mutant cancers, a combination which has been shown to lead to improvements in PFS for more than six months." (PMID 31952335, 2020). "IgA antibodies against receptors expressed by cancer cells (Her2, EGFR) could enhance neutrophil-mediated trogocytosis of cancer cells if the CD47-SIRPα innate immune cell checkpoint was simultaneously blocked." (PMID 32849639, 2020). "Hence, there has been increasing interest in the determination of EGFR levels as a basis for early-stage cancer identification." (PMID 34567646, 2020). "However, free BPD lacks selectivity against EGFR-overexpressing cancer cells, and thus will more likely induce off-target phototoxicity in vivo." (PMID 31898555, 2020).
cancer (continued). "However, cancer patients treated with EGFR inhibitors (EGFRIs) frequently develop acneiform skin toxicities, which are a strong predictor of a patient’s treatment response." (PMID 32252690, 2020). "Additionally, EGFR expression was identified to be highly expressed in a variety of human cancers, such as GBM." (PMID 33369441, 2020). "Three amplicons (KRAS, MAPK1, and CCND1) have been observed in cancer of oral cavity from Taiwanese patients, and therefore, all could possibly contribute to activation of EGFR signaling." (PMID 32974098, 2020). "Furthermore, NRP2 is required, through WDFY1 (WD-repeat and FYVE-domain-containing protein 1), to activate EGFR endocytosis in cancer cells and to maintain EGFR activities." (PMID 32766254, 2020). "Data showed that all the five anti-EGFR sdAbs could inhibit the migration and invasion of all the three cancer cell lines in a dose-dependent manner." (PMID 33023595, 2020). "Nevertheless, it remains unclear how TF expression and function are regulated in EGFR-mut cancers, particularly in the EGFR-TKI-resistant NSCLC tumors." (PMID 32923403, 2020). "The HBV−/drinker cohort contained a greater proportion of cancer pathways (EGFR tyrosine kinase inhibitor resistance, Rap1 signaling pathway, cellular senescence and PD-L1 expression and PD-1 checkpoint pathway in cancer) than immune pathways (cytokine-cytokine receptor interactions)." (PMID 32575865, 2020). "The same scenario may also exist for other signaling pathways relevant in cancer that are affected by HCMV: EGFR, PDGFR, FGF, ETBR, and IGF." (PMID 32121009, 2020). "EGF/EGFR signal transduction has been known to lead to the constitutive activation of downstream signaling pathways associated with MAPKs, STAT3, and PI3K for regulating PD-L1 expression in various cancer cells." (PMID 32204508, 2020). "Furthermore, PIC–Nal–IRI synergistically reduced cancer viability via a unique three-way mechanism (i.e., EGFR downregulation, mitochondrial depolarization, and DNA damage)." (PMID 31898555, 2020). "Honokiol inhibited cancer cell migration and invasion through downregulating EGFR phosphorylation." (PMID 32331211, 2020). "In fact, quercetin suppresses cancer cell growth and promotes phase G2 cell cycle arrest and apoptosis in EGFR-overexpressing HSC-3 and TW206 cells, thus inducing the activation of FOXO1, the knockdown of which attenuates the quercetin induction of p21 and Fas ligand (FasL) expression." (PMID 32486484, 2020). "Considering that not every cancer cell harbors the EGFR driver mutation, the T790M RMA value does not accurately represent the proportion of T790M mutant cells in a given patient." (PMID 32067121, 2020). "Besides, ciRS-7 participates in many critical cancer-related pathways, such as EGFR, PTEN/PI3K/AKT, and NF-κB." (PMID 32090067, 2020). "Although TNBCs lack ER, PR and HER2, 60–80% of these cancers express variable levels of EGFR." (PMID 32784650, 2020). "Notably, pharmacological inhibition of SLC25A1 sensitizes cancer cells to ionizing radiation, cisplatin or EGFR inhibitor treatments in lung cancer." (PMID 32103057, 2020). "EGFR is one of the most crucial genes responsible for cancer cell growth." (PMID 33424926, 2020). "Mutations in epidermal growth factor receptor (EGFR), as well as rearrangement of ROS1 and anaplastic lymphoma kinase (ALK), are suggested as the first-line treatment for metastatic LC, which contribute a lot to cancer patient OS." (PMID 32104702, 2020). "Therefore, CICERO’s improved sensitivity in detecting these fusions can potentially expand the eligibility for treatment with EGFR inhibitors in cancer patients." (PMID 32466770, 2020). "Some cancer-related SNPs at five loci—TERT, butyrophilin-like 2, TP63, bromodomain PHD finger transcription factor, and high-mobility group box protein 1—showed significant effects on EGFR-mutated LADC." (PMID 33126605, 2020).
cancer (continued). "In addition, erlotinib is also a RTK inhibitor, which inhibited the activation of epidermal growth factor receptor (EGFR), and has been administrated to treat many cancers." (PMID 32742495, 2020). "Epidermal growth factor receptor (EGFR) is upregulated in numerous cancers." (PMID 33050646, 2020). "Yet, EGFR-TKIs have shown promising results in the treatment of other cancers." (PMID 32784650, 2020). "Although accumulating evidences suggested the activation of EGFR contributes to PD-L1 expression in several cancers, it is still unknown whether EGF/EGFR signal was involved in PD-L1 expression in HCC." (PMID 33324209, 2020). "Among the family of human epidermal growth factor receptors (EGFR), HER2 has been linked to the activation of PI3K/AKT as well as Ras/Raf/MEK/MAPK, which has been associated with features of several cancer types in terms of the ability to divide, migrate and differentiate." (PMID 32410348, 2020). "Poor efficacy in the clinical treatment of cancers overexpressing EGFR may be due to the cross-talk between EGFR and MET14,15." (PMID 32001707, 2020). "The development and the use of three generations of EGFR inhibitors in the clinical setting significantly improved the prognosis of NSCLC cancer patients, in particular in ~10% to 15% of cases of white patients and even 50% of cases of Asian NSCLC patient, harboring activating EGFR mutations." (PMID 32517369, 2020). "Epidermal growth factor receptor (EGFR) and its ligands are involved in cancer pathogenesis." (PMID 33024132, 2020). "However, many patients receiving first- and second-generation EGFR-TKIs will require rebiopsies when their cancers acquire resistance." (PMID 32907572, 2020). "The nicotine and derivatives may mediate oncogenic signaling via nAChR, β-AR, and EGFR and combined with the effects of antiapoptosis in mitochondria that contribute to cancer progression." (PMID 31956359, 2020). "This study demonstrates that these anti-EGFR sdAbs may become good alternative of mAbs for cancer therapy." (PMID 33023595, 2020). "EGFR mediates the entry of HIV+ exosomes into cancer cells, possibly enriched in endosomes." (PMID 32051269, 2020). "Moreover, consistent with its role as a NRP1 ligand, Gal-1 negatively controls p27 levels, a mechanism previously found to enable EGFR upregulation in cancer cells." (PMID 32784465, 2020). "The over-activation of EGFR in cancer is a major reason for metastasis." (PMID 32121107, 2020). "OPN interacts with integrins to induce the activation of phosphoinositide 3-kinase (PI-3Kinase), mitogen-activated protein kinase (MAPK), phospholipase C-γ and protein kinase C through the c-Src-dependent transactivation of the epidermal growth factor receptor (EGFR) in cancer cells." (PMID 32862200, 2020). "Preclinical studies have suggested that targeting mTOR could improve the efficacy of EGFR inhibitors in various human cancers, including TNBC." (PMID 32286420, 2020). "At the same time, the study also pointed out that the resistance to anti-EGFR agents in cancer cells will change from temporary to irreversible as the agents last longer, which put forward a new thinking on the choice of the targeted agents and the design of the treatment regimens." (PMID 32665850, 2020). "This mechanistic understanding will be key to unravelling the functional consequences of direct anti-EGFR targeted and indirect EGFR-impacting cancer therapies on the secretion of pro-tumoural EVs and on their effects on drug resistance and microenvironment subversion." (PMID 33302515, 2020). "Moreover, recent data have provided evidence for EGFR/Ras/Mek signaling to control PD-L1 expression in cancers." (PMID 33194623, 2020). "Consequently, EGFR inhibition with monoclonal antibodies or tyrosine kinase inhibitors is an FDA approved cancer therapy." (PMID 32054454, 2020). "Interestingly, both of EGFRvIII and wild type EGFR are present in the mitochondria whereby they protect cancer cells from apoptotic cell death." (PMID 32807793, 2020).
cancer (continued). "The importance of NRP1 in regulating EGFR signaling in cancer cells has been described previously." (PMID 32784465, 2020). "Furthermore, mitochondria have been reported to depend on the EGFR, and this sensitivity is crucial for metabolic homeostasis of cancer cells." (PMID 32443749, 2020). "All of these data suggest that FGFR-TKIs could be a possible solution to EGFR-TKI-resistant cancers expressing EGFR T790M-L858R." (PMID 33092268, 2020). "But EGFR signaling activation increased MUC1 gene expression in some cancer cell lines." (PMID 32938364, 2020). "However, the natural and pathological significances of nuclear EGFR in cancers remain mostly unidentified." (PMID 32321917, 2020). "EGFR is a protein involved in the pathogenesis and progression of different carcinoma types." (PMID 32942549, 2020). "The EGFR expression and interpretation could be diverse based on pathologists' visual scoring or the fraction of carcinoma staining." (PMID 33295294, 2020). "Blockade of ITGα3 expression evoked anti-cancer effect by inhibiting EGFR signalling pathways." (PMID 30808960, 2019). "We further hypothesized that the EGFR/Eps8 complex inhibitor could negatively affect the survival of cancer cells by suppressing the downstream signaling of EGFR/Eps8." (PMID 31118055, 2019). "One speculation has been that EGFR is simply unimportant for those cancers that are innately resistant to EGFR kinase inhibitor." (PMID 31508364, 2019). "In addition, membrane rafts disruption has been shown to alter EGFR signaling that affects various cellular processes in many cancers, including cell proliferation, apoptosis inhibition, cell migration, angiogenesis and metastasis." (PMID 31477154, 2019). "Finally, in addition to trafficking to the nucleus, EGFR can also translocate to mitochondria and regulate mitochondrial function, which has potential consequences for cancer biology and metastatic potential." (PMID 30890751, 2019). "Epidermal growth factor receptor (EGFR) is upregulated in many cancers including renal cancer." (PMID 30770799, 2019). "In this study, we combined genomic information on cancer cell lines with drug response data to identify potential biomarkers that could predict response to EGFR inhibitors." (PMID 30787334, 2019). "Accordingly, inhibitors of VEGFR and EGFR tyrosine kinases have been used to treat several cancers." (PMID 30995736, 2019). "Several proteins have been shown to regulate EGFR dynamics in cancer." (PMID 31805710, 2019). "In line with this, clinical trials confirmed that patients with KRAS-mutant cancers generally have a poor response to the first generation of EGFR inhibitors, such as erlotinib and gefitinib, and the presence of KRAS mutations is used as a biomarker to exclude patients for EGFR inhibitor therapy." (PMID 31612108, 2019). "Epidermal growth factor receptor (EGFR), which plays an important role in cell signaling, enhanced cell survival and proliferation, has been suggested as molecular target for the development of novel cancer therapeutics." (PMID 30897725, 2019). "Additionally, since clathrin- and caveolin-mediated endocytosis controls the degradation and recycling of EGFRs, the deregulated EGFR endocytosis results in prolonged activation, which can also lead to the development of cancer." (PMID 31805710, 2019). "EGF is considered as a ligand part of EGFR, and previous studies have demonstrated that its activation could stabilize and enhance the β-catenin nuclear accumulation in cancer." (PMID 31171012, 2019).
cancer (continued). "Inefficient elimination of EGFR-mutant cancer cells by gefitinib’ lower CNS concentration than erlotinib’s may explain the higher incidence of brain metastases after failure of gefitinib compared to erlotinib." (PMID 31822734, 2019). "Alterations of EGFR in cancers and application of EGFR inhibitors." (PMID 31508364, 2019). "To improve tissue penetration and shorten photosensitivity, we have recently introduced nanobodies, also known as VHH (variable domains from the heavy chain of llama heavy chain antibodies), for targeted PDT of cancer cells overexpressing the epidermal growth factor receptor (EGFR)." (PMID 31544832, 2019). "Additionally, we observed that the antitumour efficacy of single-agent CAR exosomes induced potent TGI in EGFR- or HER2-positive human cancer cell line models or patient-derived xenograft models." (PMID 31554797, 2019). "Besides genes expressed in common with hESCs, cancer cells expressed Epiregulin (EREG) and Amphiregulin (AREG) of the EGF-receptor (EGFR) pathway, generally associated with progressed cancer." (PMID 31758153, 2019). "In this guideline, we generically name EGFR mutation, ALK translocation, ROS1 translocation, and BRAF mutation as driver oncogenes that might be the direct cause of cancer evolution." (PMID 31049758, 2019). "Consistent with this hypothesis, their data indicate that CARMA3 and Bcl10 are required for EGFR-induced NF-κB activation in both EGFR-expressing human cancer cell lines and mouse embryonic fibroblasts." (PMID 30814996, 2019). "EGF receptor (EGFR) is up‐regulated in many types of cancer." (PMID 31638339, 2019). "As a receptor tyrosine kinase, EGFR's kinase activity has been serving as the primary target for developing cancer therapeutics, namely the EGFR inhibitors including small molecules targeting its ATP binding pocket and monoclonal antibodies targeting its ligand binding domains." (PMID 31508364, 2019). "Therefore, RAS testing including KRAS exons 2, 3 and 4 (codons 12, 13, 59, 61, 117 and 146) is mandatory before treatment with anti-EGFR therapy in cancer patients." (PMID 31673240, 2019). "Increased levels of nuclear EGFR have been correlated with poor prognosis in many cancers." (PMID 31426451, 2019). "More than 50% of TNBCs strongly express EGFR and these cancers respond poorly to chemotherapy." (PMID 31069012, 2019). "Moreover, these mutations account for nearly 9–11% of all cancers documented with EGFR mutations in NSCLC, representing the third most common type of EGFR mutations, after L858R and exon 19 deletions." (PMID 31739412, 2019). "A possible scenario for the EphrinB2-independent EphB4 cancer-promoting effects come from the observation that EphB4 is able to bind and eventually trans-activate other membrane TK receptorial systems such as the EGFR." (PMID 31270394, 2019). "EGFR is one of the most studied receptor tyrosine kinases in the cancer drug target field." (PMID 31116768, 2019). "EGFR are major contributors of a complex signaling cascade in cancer cells that modulates growth, signaling, differentiation, adhesion, migration and survival, therefore making EGFR an attractive candidate for anti-cancer targeting and therapy." (PMID 31140150, 2019). "The human epidermal growth factor tyrosine kinase receptor (EGFR/ERBB) family, which includes four members: HER1 (EGFR, ErbB1), HER2 (Neu, ErbB2), HER3 (ErbB3), and HER4 (ErbB4) have been associated with many human cancers." (PMID 31470531, 2019). "As a result, EGFR has become an attractive molecular target for cancer therapy, including PC." (PMID 30674340, 2019). "RNF128 regulates the EGFR/MAPK/MMP-2 pathway to drive these aggressive cancer features in ESCC." (PMID 31216681, 2019).